BAMBI (BMP and activin membrane bound inhibitor)
Description:
Negatively regulates TGF-beta signaling.
Synonyms: NMA
Tractability: Antibody: its Gene Ontology location is reachable by antibodies, with high confidence; UniProt predicts a signal peptide or a membrane-spanning region. PROTAC: ubiquitination databases record sites on it.
Gene: Protein-coding gene on chromosome 10 (28,677,510 to 28,682,932, forward strand). Ensembl gene ENSG00000095739.
Subcellular location: Membrane
Subcellular location (Human Protein Atlas): Vesicles; Lipid droplets; Nucleoli fibrillar center
Pathways (Reactome):
Signal Transduction: Downregulation of TGF-beta receptor signaling
Gene Ontology:
Molecular function: frizzled binding; protein binding; type II transforming growth factor beta receptor binding
Biological process: cell migration; negative regulation of BMP signaling pathway; negative regulation of osteoblast differentiation; negative regulation of transforming growth factor beta receptor signaling pathway; positive regulation of canonical Wnt signaling pathway; positive regulation of cell population proliferation; positive regulation of DNA-templated transcription; positive regulation of epithelial to mesenchymal transition; regulation of cell shape; transforming growth factor beta receptor signaling pathway
Cellular component: cytoplasm; plasma membrane; membrane
Genetic constraint (gnomAD): Loss-of-function variants: 21 observed, 23.23 expected, observed/expected ratio (o/e) 0.9, 90% interval 0.64 to 1.3. The upper end of that interval is the gene's LOEUF score, 1.3, which puts it in group 5 of 6, group 1 being the genes least tolerant of losing a copy. Missense variants: 388 observed, 333.8 expected, observed/expected ratio (o/e) 1.16, 90% interval 1.07 to 1.26. Synonymous variants: 156 observed, 126.8 expected, observed/expected ratio (o/e) 1.23, 90% interval 1.08 to 1.4.
Homologues: Orthologues: chimpanzee BAMBI (99% identical), macaque BAMBI (99% identical), rat Bambi (96% identical), pig BAMBI (94% identical), mouse Bambi (93% identical), dog BAMBI (90% identical), guinea pig BAMBI (85% identical), tropical clawed frog bambi (84% identical), zebrafish bambia (74% identical), zebrafish bambib (68% identical). Paralogues in human: CATIP (17% identical).
Diseases named in the same sentence as BAMBI in open-access papers:
BAMBI is named in the same sentence as 77 diseases in open-access papers, as found by Europe PMC text mining. Sharing a sentence is not in itself a finding about the gene and the disease. The quoted sentences say what the papers report.
colorectal cancer (10 papers, 2011 to 2025). A primary or metastatic malignant neoplasm that affects the colon or rectum. "This study addresses a critical gap in understanding colorectal cancer (CRC) radiation resistance by identifying BAMBI, GADD34, NFKBIA, and NFKBID as key modulators of tumor progression and response to radiotherapy." (PMID 40332515, 2025). "miR-17-5p is also regulated by other lncRNAs or target other mRNAs and then, promotes tumorigenesis, for example, MIR17HG promotes colorectal cancer progression via miR-17-5p, miR-17-5p promotes angiogenesis in nasopharyngeal carcinoma via targeting BAMBI." (PMID 35365175, 2022). "For instance, elevated BAMBI expression was correlated with poor prognosis in colorectal cancer (CRC), while BAMBI inhibition upregulated TGF-β signaling, resulting in reduced CRC cell viability and motility in vitro and in vivo." (PMID 36109807, 2022). "Studies have shown that inhibition of BAMBI expression in colorectal cancer can upregulate TGF-β signaling, leading to elevated levels of p-Smad2 and p-Smad3." (PMID 31186664, 2019). "Conversely, BMP and Activin Membrane-bound Inhibitor, BAMBI, is upregulated in colorectal cancer and is under direct regulation of the Wnt pathway, a component of a gene expression profile that predicts metastasis." (PMID 26447543, 2015). "High expression of BAMBI has been shown to predict metastatic potential in colorectal cancer and it is epigenetically silenced in high grade bladder carcinomas." (PMID 22171747, 2011). "The over-expression of BAMBI has also been detected in colorectal cancer." (PMID 31623294, 2019). "In sharp contrast to colorectal cancer, human lung tumors have reduced BAMBI expression." (PMID 29799477, 2018). "The present study has focused exclusively on the effects of four gene knockdown on drug sensitivity in colorectal cancer cells, without delving into the molecular mechanisms through which three of these key genes – BAMBI, MAPK8IP2, and BMP7 – regulate oxaliplatin sensitivity." (PMID 41395597, 2025).
hepatocellular carcinoma (9 papers, 2010 to 2025). A malignant tumor that arises from hepatocytes. "Chronic liver diseases have a high risk of hepatocellular carcinoma (HCC), and BAMBI was shown to exert tumor-promoting as well as tumor-protective functions." (PMID 36834884, 2023). "A recent study on hepatocellular carcinoma (HCC) found that ferroptosis is regulated by the PPARGC1A/BAMBI/ACSL5 axis, with METTL3 and WTAP inhibiting PPARGC1A in an m6A- and YTHDF2-dependent manner." (PMID 40271153, 2025). "In HepG2 hepatocellular carcinoma cells, TGFβ has been reported to increase mRNA levels for BAMBI, whereas endotoxin (LPS) downregulated mRNA for BAMBI in murine hepatic stellate cells via TLR4." (PMID 20886049, 2010). "In HepG2 hepatocellular carcinoma cells, TGFβ was reported to increase mRNA for BAMBI." (PMID 20886049, 2010). "Our study aimed to correlate hepatocyte BAMBI protein levels in hepatocellular carcinoma (HCC) with T stage, lymph node invasion, vessel invasion, grading, tumor size and Union for International Cancer Control (UICC) stage, as well as with liver inflammation and fibrosis stages." (PMID 39457709, 2024).
liver fibrosis (9 papers, 2010 to 2025). "In line with these in vitro findings, the increased level of microRNA-942 in HBV-infected patients with F3 and F4 liver fibrosis was associated with low BAMBI mRNA and protein." (PMID 36834884, 2023). "Bile duct ligation causes severe liver fibrosis, and HSCs from these mice expressed little BAMBI." (PMID 36834884, 2023). "The therapeutic effects of DZNep as epigenetic drug in liver fibrosis are associated with the regulation of EZH2 towards direct target genes encoding TGF-β1 pseudoreceptor BAMBI, anti-inflammatory cytokine IL10 and cell cycle regulators CDKN1A, GADD45A and GADD45B, which are also regulated by JMJD3." (PMID 33391480, 2021). "In liver fibrosis, BAMBI expression is downregulated in both rodent models and human patients, contributing to disease progression." (PMID 40260391, 2025). "Experimental evidence convincingly demonstrated that BAMBI overexpression is able to protect against liver fibrosis." (PMID 36834884, 2023). "HSCs isolated from the liver of mice with liver fibrosis expressed less BAMBI mRNA than quiescent cells." (PMID 36834884, 2023). "The function of BAMBI as a TGF-β type I pseudoreceptor provides strong evidence for an inhibitory role in hepatic fibrosis." (PMID 36834884, 2023). "Adipose tissue dysfunction is a key factor in the pathogenesis of NAFLD, and adiponectin, which was shown to upregulate hepatocyte and HSC BAMBI expression, is low in obesity and thus provides a link between obesity and liver fibrosis." (PMID 36834884, 2023). "Experimental findings so far suggest that BAMBI overexpression protects from liver fibrosis, making it a promising therapeutic target." (PMID 36834884, 2023). "Taken together, there is strong evidence for HSC-expressed BAMBI as a central molecule in liver fibrosis." (PMID 36834884, 2023). "In the development of liver fibrosis, miR-942 expression was up regulated in activated HSCs and exhibited an inverse relationship with BAMBI expression." (PMID 37621844, 2023). "Hepatic BAMBI expression in liver fibrosis patients with advanced stage is lower as compared to those with mild or no fibrosis." (PMID 33391480, 2021). "In murine hepatic stellate cells, mRNA and protein for BAMBI were reported to be decreased by LPS and this resulted in enhanced signaling of TGFβ in vitro and in increased liver fibrosis in vivo." (PMID 20886049, 2010). "In mice the significance of BAMBI's interaction with TGFβ signaling and the resulting effects on fibrosis were recently examined in models of progressive liver fibrosis." (PMID 20886049, 2010). "Recent studies suggest that BAMBI overexpression can protect against liver fibrosis." (PMID 40260391, 2025). "Thus, enhancing BAMBI expression to block TGF-β signaling seems a reasonable approach to prevent liver fibrosis." (PMID 36834884, 2023). "Convincing experimental evidence showed that overexpression of BAMBI protects from liver fibrosis." (PMID 36834884, 2023). "The activation of TGF-β signaling decreases the bone morphogenetic protein and activin membrane-bound inhibitor (BAMBI), SMAD7, and increases the SMAD2/3/4 proteins, resulting in the excessive production of ECM and the progression of liver fibrosis." (PMID 35051234, 2022). "BAMBI and Smad7 play important roles in TGF-β signal transduction in the context of the pathological development of liver fibrosis." (PMID 27594891, 2016).
ovarian carcinoma (6 papers, 2020 to 2025). A malignant neoplasm originating from the surface ovarian epithelium. "Overexpression of BAMBI in ovarian cancer cells was previously associated with enhanced cellular proliferation, migration and reduced apoptosis, but a significant effect on OS has not yet been reported in HGSTOC." (PMID 34238352, 2021). "The correlations between the expression levels of RFXANK, CDC42EP3 and BAMBI and prognosis in ovarian cancer patients were analyzed by the PrognoScan database." (PMID 34616622, 2021). "Given the up-regulated RFXANK and down-regulated CDC42EP3 and BAMBI in two independent ovarian cancer datasets from Oncomine, we expected CDC42EP3 as a potential prognostic target that needs further investigation." (PMID 34616622, 2021). "CHRD, NKX2-5 were also co-expressed in bladder and ovarian cancer datasets whereas BAMBI was only reported in breast and lung datasets." (PMID 31973134, 2020). "BAMBI is also reported to be overexpressed in breast and ovarian cancer and co-translocate with Smads into the nucleus upon TGF-β treatment." (PMID 31973134, 2020). "Notably, prior studies have reported that BAMBI overexpression in ovarian cancer promotes cell proliferation and migration, while also reducing TGF-β-induced apoptosis more than fourfold." (PMID 40332515, 2025). "Besides, the expression of BAMBI was significantly higher in ovarian cancer through TGF-beta signaling." (PMID 34188683, 2021).
breast carcinoma (5 papers, 2016 to 2025). "Dependency in these lines did not correlate with BAMBI gene expression, copy number or mutation, suggesting an epigenetic predictor and a role for SE acquisition in BAMBI dependence in breast cancer." (PMID 32584896, 2020). "Reduced BAMBI expression enhances MDSC tumor infiltration and T cell suppression, driving radioresistance and metastasis in breast cancer, while AAV-mediated BAMBI restoration synergizes with radiotherapy to improve local control and suppress distant tumors." (PMID 40986143, 2025).
melanoma (5 papers, 2011 to 2025). A malignant, usually aggressive tumor composed of atypical, neoplastic melanocytes. "These include known melanoma-promoting proteins such as fibronectin and tenascin C, but also novel promising candidates such as BAMBI, a negative regulator of TGF-beta signaling." (PMID 27689402, 2016). "Evidence for BAMBI implication in melanoma comes mainly from transcript overexpression since protein levels are low." (PMID 27689402, 2016). "Additional co-expression studies with defined gene signatures using Oncomine suggest an association of BAMBI and FKBP10 with the angiogenic process in melanoma and with regeneration after HRAS induced cell transformation, respectively." (PMID 27689402, 2016). "We compared BAMBI expression in a panel of 19 different tumor cell types, and found overexpression most prominent in melanoma cell lines (n = 41)." (PMID 27689402, 2016). "Connective tissue growth factor in turn controls expression of BMP7 and the TGFβ pseudo-receptor BAMBI and contributes to tumour progression by increasing migratory and invasive potential of melanoma cells." (PMID 21673687, 2011). "The role of BAMBI in melanoma progression has yet to be established." (PMID 27689402, 2016). "When compared to other types of skin cancer such as basal cell carcinoma or squamous cell carcinoma, BAMBI showed selective overexpression in melanoma and strong co-expression (0.815) with the established melanoma gene EDNRB, but also with HEY1 (0.759), a gene important for vascular development." (PMID 27689402, 2016). "It is tempting to speculate that BAMBI participates in melanoma progression via influencing stem cell differentiation or participating in leukocyte mimicry of circulating melanoma cells." (PMID 27689402, 2016). "Interestingly, a correlation was observed between CTGF and BAMBI expression levels in melanoma cell lines (r=0.854)." (PMID 21673687, 2011). "Whereas the role of TNC (tenascin C) and FN1 (fibronectin 1) in melanoma development is well documented, implication of MARCKS, RCN3, BAMBI, PEA3/ETV4 and the FK506 family members FKBP7, FKBP10 and FKBP11 in melanoma progression is unclear." (PMID 27689402, 2016). "Overexpression or knockdown (KD) of BAMBI did not affect the in vivo tumor growth of either MC38 colon cancer or B16 melanoma." (PMID 38099498, 2023). "BAMBI expression (5.556-fold up in melanoma vs normal skin and 10.7-fold vs other cancers) has not been previously associated with melanoma." (PMID 27689402, 2016).
bladder cancer (4 papers, 2010 to 2023). "The function of BAMBI in cancer progression, similar to SMAD7 and BMP7, appears to be context dependent; in colorectal malignancies BAMBI is pro-tumorigenic whereas in the lung and bladder cancer BAMBI exhibits anti-tumor properties." (PMID 29799477, 2018). "As was the case in lung carcinomas, transient transfection of BAMBI siRNA markedly reduced the migratory response to TGF-β1 in bladder cancer cell lines." (PMID 29799477, 2018). "Specific genes such as RASSF1A, RARB, BAMBI and the SFRP family have been associated with higher grade and higher stage bladder cancer." (PMID 20808801, 2010). "DNA methylation is reported to be involved in BAMBI regulation in high-grade bladder cancer." (PMID 38099498, 2023).
colon cancer (4 papers, 2021 to 2025). "A former study indicated that highly expressed BAMBI could contribute to colon cancer metastasis through Wnt/beta-catenin in mice models." (PMID 34188683, 2021). "Previous studies have established that BAMBI is controlled by SMAD3/4 signaling and Wnt/β-catenin signaling in colon cancer cells." (PMID 38099498, 2023).
nasopharyngeal carcinoma (4 papers, 2019 to 2022). A carcinoma arising from the nasopharyngeal epithelium. "Exosome-derived miR-17-5p can promote angiogenesis in nasopharyngeal carcinoma by targeting BAMBI, and can promote proliferation and migration of nasopharyngeal carcinoma cells by regulating the AKT/VEGF-A signaling pathway." (PMID 33828985, 2021). "For example, nasopharyngeal carcinoma-derived exosomal miR-17-5p promoted angiogenesis of nasopharyngeal carcinoma via targeting BAMBI." (PMID 33834074, 2021).
Obesity (4 papers, 2019 to 2023). Accumulation of substantial excess body fat. "Given that hepatic steatosis is closely associated with obesity and insulin resistance, we assessed the impact of adipose BAMBI deletion on hepatic lipid deposition." (PMID 33158991, 2021). "Such enhanced understanding of the interplay between BAMBI, ROS, and adipocyte differentiation could provide novel directions for the prevention of obesity-associated conditions." (PMID 33158991, 2021). "Further, we utilized a new mouse model in which BAMBI has been deleted specifically in adipocytes to characterize the pathophysiological role of BAMBI in an HFD-induced obesity model." (PMID 33158991, 2021). "Adipose-specific deletion of BAMBI promoted HFD-induced obesity, impaired adipose function, and deteriorated glucose intolerance and insulin resistance." (PMID 33158991, 2021). "We now show that BAMBI deficiency in adipocyte caused hypertrophy and hyperplasia of adipocytes and an elevated NOX4-derived ROS level during the development of obesity." (PMID 33158991, 2021). "Within this context, disruption of BAMBI in adipocytes promoted obesity in high-fat diet-fed mice." (PMID 36834884, 2023). "Consistently, our findings indicated that BAMBI may be a reactive oxygen regulator to affect adipogenesis, thereby controlling obesity and metabolic syndrome." (PMID 33158991, 2021). "Thus, BAMBI may be a potential therapeutic target for ameliorating obesity and obesity-related metabolic disorders." (PMID 33158991, 2021). "Thus, here we generated fat-specific BAMBI knockout mice and found that BAMBI knockout can lead to HFD-induced obesity and insulin resistance, thereby deepening our understanding of BAMBI function." (PMID 33158991, 2021).
osteosarcoma (4 papers, 2017 to 2022). A usually aggressive malignant bone-forming mesenchymal neoplasm, predominantly affecting adolescents and young adults. "In general, 5 MAGs (MAP3K5, PML, WDR1, BAMBI, and GNPDA2) correlated with the prognosis of osteosarcoma were screened for the construction of the risk model." (PMID 34188683, 2021). "The expression of gene WDR1 (p = 0.006), PML (p = 0.005), MAP3K5 (p = 0.010), and GNPDA2 (p = 0.009) were significantly higher in normal bone sample while in osteosarcoma samples, the expression of BAMBI (p = 0.006) was significantly higher." (PMID 34188683, 2021). "The selected 5 MAGs (MAP3K5, PML, WDR1, BAMBI, and GNPDA2) were identified as prognostic-related genes for osteosarcoma, and a novel macrophage-associated risk model was constructed based on these 5 MAGs." (PMID 34188683, 2021). "It has been reported that BAMBI modulates the proliferation of human osteosarcoma cells by regulating the expression of cell cycle proteins, therefore we examined if BAMBI knockdown influences the expression of cell cycle regulatory molecules in Y-MESO-27 and Y-MESO-14 cells." (PMID 36109807, 2022). "The overexpression of BAMBI promotes the growth and invasion of human osteosarcoma cells." (PMID 36225939, 2022). "Similarly, our study reported that high expression of BAMBI would result in a poor prognosis of osteosarcoma, which implied that BAMBI could be a new target for the treatment of osteosarcoma." (PMID 34188683, 2021). "BAMBI, a transforming growth factor beta (TGFB) inhibitor is up-regulated in metastatic carcinomas including colorectal and osteosarcoma." (PMID 29199959, 2017). "BAMBI has also been reported to regulate cyclin D1, CDK2, and CDK6 in human osteosarcoma cells." (PMID 36109807, 2022).
lung carcinoma (3 papers, 2016 to 2022). "Upregulation of TGF-β1 and SMAD2/3/4, increased SMAD2/3 phosphorylation and a loss of BAMBI expression were prominent in the lung cancer cell lines A549 and H1975." (PMID 29799477, 2018). "Bladder tumors display a BAMBI expression pattern similar to that seen in lung cancer." (PMID 29799477, 2018).
prostatic hyperplasia (3 papers, 2016 to 2021). "Here we report that LPS/TLR4 signalling induces down-regulation of the bone morphogenic protein and activin membrane-bound inhibitor (BAMBI), which enhances TGF-β signalling in the EMT process during prostatic hyperplasia." (PMID 27243216, 2016). "In this study, we report that BAMBI acts as a regulator between LPS/TLR4 signalling and TGF-β-induced EMT in vitro during prostatic hyperplasia." (PMID 27243216, 2016).